BRAF (B-Raf proto-oncogene, serine/threonine kinase)
Diseases named in the same sentence as BRAF in open-access papers (continued):
Sharing a sentence is not in itself a finding about the gene and the disease.
melanoma (continued). "Patients with unresectable stage IIIC/IV BRAF V600E/K mutant melanoma were randomized to treatment with atezolizumab, vemurafenib and cobimetinib or placebo, vemurafenib and cobimetinib." (PMID 36505793, 2022). "A retrospective analysis of several clinical trials, indeed, concluded that nivolumab has comparable efficacy in patients with WT or mutant BRAF melanoma." (PMID 35234863, 2022). "Flow cytometry was used to test TNFR1, TNFR2 and CD271 expression on, as well as NF-kB phosphorylation in human BRAF-mutant melanoma." (PMID 35879777, 2022). "In most of the 218 BRAF-mutant melanoma patients showing tumor progression, 2L treatment was initiated, of which 135 patients received BRAF ± MEKi and CPI in sequence (55.6%) and were thus eligible for our analysis." (PMID 35565212, 2022). "Two randomized trials have investigated intermittent dosing regimens with BRAF and MEK inhibitors for the treatment of BRAF-mutated advanced malignant melanoma." (PMID 36233569, 2022). "Next, we examined the data reported recently by the Molloy laboratory, that analyzed samples coming from patients with metastatic BRAF/NRAS melanoma." (PMID 36776379, 2022). "Further, prior knowledge of the hotspot SNV is required for this ctDNA-based monitoring, as it has been shown that the monitoring is unsuccessful for melanoma patients that lack BRAF V600E SNV." (PMID 35205608, 2022). "MEK2 Q60P mutation was identified as a resistance driver in 3 out of 5 BRAF mutant melanoma patients under dual inhibition of MEK and BRAF, while ERK inhibitors can attenuate the elevated ERK signaling and reverse the refractory phenotype 75." (PMID 35966590, 2022). "Resistance to BRAF inhibitors in BRAF V600E melanoma develops when secondary mutations and/or changes in basal protein expression allow for the activation of MEK/ERK signaling even in the presence of BRAF inhibitors." (PMID 36358868, 2022). "The most common immuno- and/or targeted therapies prescribed for the treatment of advanced melanoma in this case series were PD-1 blocker (pembrolizumab, n = 29), BRAF inhibitor (dabrafenib, n = 14) and MEK inhibitor (trametinib n = 14)." (PMID 35681781, 2022). "As a proof of concept, combining treatment of ceritinib and trametinib in vitro and in vivo demonstrated synergistic antitumor activity in PD-CSF-CTCs and BRAF inhibitor-resistant melanoma cells." (PMID 35213727, 2022). "There is also an overlap in genes associated with melanoma and the RASopathies, in that mutations in BRAF, NRAS, and NF1 in melanoma are also well‐known RASopathy‐associated genes." (PMID 35266292, 2022). "In fact, the combination of the BRAF inhibitor encorafenib and the MEK inhibitor binimetinib has been approved as a first-line treatment in patients with BRAF V600E mutated melanoma in the US and Europe." (PMID 36077604, 2022). "In this study, we identify the MAPK p38 as a novel mediator of the adaptive response of melanoma cells to BRAF-targeted therapy." (PMID 35944584, 2022). "Here, we obtained several relevant findings that give new insights into the role of treatment sequencing in melanoma therapy and the outcome of BRAF-mutant melanoma patients upon primary treatment failure." (PMID 35565212, 2022). "Three clinical trials, two phase 3 and one phase 2, have been designed to compare the efficacy of anti-PD-L1 in combination with BRAF/MEK inhibitors in BRAFV600-mutant melanoma." (PMID 36428582, 2022). "Biochemical studies revealed that fibroblast‐derived matrices enhance the activation of the non‐canonical NF‐κB2 pathway that account for most of the melanoma cell tolerance to BRAF/MEK inhibition." (PMID 34957688, 2022). "Overall, our data indicate that the HDAC inhibitor ITF2357 has a potential as melanoma therapy candidate since it targets oncogenic BRAF protein." (PMID 36009541, 2022).
melanoma (continued). "Currently, adjuvant pembrolizumab (anti-PD1), nivolumab (anti-PD1), or combination dabrafenib (BRAF inhibitor) and trametinib (MEK inhibitor) are recommended for resected stage III melanoma (dependant on BRAF status)." (PMID 35778691, 2022). "Recently, a growing group of researches showed that oncogenic BRAF can decrease the ability of the immune system to recognize melanoma cells." (PMID 36531226, 2022). "Despite recent advances in the development of BRAF kinase inhibitors (BRAFi) for BRAF-mutant melanomas, development of resistance remains a major clinical problem." (PMID 35944584, 2022). "On the one hand, enhanced autophagy mediates the extracellular ATP secretion, which confers the invasion and migration of melanoma cells as well as drug resistance to BRAF-targeted therapy." (PMID 36003368, 2022). "BRAF-mutant melanomas are sensitive to blockade of this pathway with BRAF inhibitors which reduce tumour cell survival and proliferation." (PMID 35366166, 2022). "Future studies should investigate the therapeutic potential of a VEGFR inhibitor to treat BRAF-resistant melanoma; however, antiangiogenic administration should be used with caution." (PMID 35954441, 2022). "We next investigated the effects of YAP activation in two BRAF mutant melanoma and five colorectal cancer cell lines." (PMID 36476495, 2022). "In view of drug resistance and other problems arising from the BRAF inhibitor alone, the combination treatment of MEK and BRAF inhibitors was a better clinical achievement for melanoma patients with the BRAF V600E mutation." (PMID 36551302, 2022). "A recent phase 2 trial in melanoma compared continuous versus intermittent dosing of BRAF and MEK inhibitors and found intermittent dosing of inhibitors did not improve progression-free survival." (PMID 36418460, 2022). "In the Asian population, BRAF melanoma and, proportionally, V600K melanoma seem to be a rarer entity." (PMID 35160279, 2022). "Specifically, YAP confers resistance to BRAF inhibitors by inducing actin cytoskeleton remodeling in melanoma and other tumors, and cytoskeletal tension itself has been shown to affect chemotherapeutic drug sensitivity of cancer cells." (PMID 35440004, 2022). "Exceptions are the combination of BRAF and MEK inhibitors for BRAF mutated melanoma, PCPs and PXAs as also applied in our cohort." (PMID 35864412, 2022). "In BRAF-mutant melanomas, therapy resistance to vemurafenib is supported by the Sterol Regulatory Element-Binding Protein (SREBP1) activation and the upregulation of the S1 P-dependent signaling pathway." (PMID 35681673, 2022). "HuHER3-8 in combination with a BRAF inhibitor reduced tumor growth and increased durable response in mutant BRAF models of melanoma." (PMID 36271429, 2022). "Melanoma is considered one of the most aggressive forms of skin cancer and the use of BRAF inhibitors, such as vemurafenib and dabrafenib, is revolutionizing the treatment of melanoma." (PMID 36559016, 2022). "MEK1 inhibitors, in combination with rapid accelerated fibrosarcoma B-type (BRAF) inhibitors, have dramatically improved tumor response rate and progression-free survival in patients with stage III or IV metastatic BRAF-mutated melanoma." (PMID 35744803, 2022). "BET confers YAP/TAZ-mediated drug resistance in vemurafenib-treated BRAF mutant melanoma cells, which can be re-sensitized by JQ1." (PMID 35883668, 2022). "Recientemente, se ha propuesto que la combinación de metformina y anti-VEGF podría ser útil en pacientes con melanoma BRAF y mutación V600E, resistentes a tratamiento con inhibidores BRAF." (PMID 35569426, 2022). "The most common activating genetic alterations in melanoma include v-Raf murine sarcoma viral oncogene homolog B (BRAF) (~50%), RAS viral oncogene homolog (RAS) (~25%) and Neurofibromin 1 (NF1) (~15%) mutations." (PMID 35565222, 2022).
melanoma (continued). "BRAF inhibitor-resistant melanoma cell lines, in which an increased expression of PD-L1 occurs, have shown the ability to evade the host’s immune system." (PMID 35628540, 2022). "In this case, DCA can further enhance oxidative metabolism, thereby increasing the dependency of BRAF inhibitor-resistant melanoma cells on glutamine." (PMID 35409102, 2022). "The persister cell states in our zebrafish models share conserved mechanisms with human melanoma cells depleted for MITF or following BRAF inhibitor drug treatment." (PMID 35929478, 2022). "They met on June 13-15, 2022, to develop recommendations for widespread BRAF testing for melanoma and CRC in LA." (PMID 36589179, 2022). "In conclusion, we identified 13C-glucose fluxomic as a potential marker of response to BRAF/MEK inhibition in YUMM1.7 melanoma xenografts." (PMID 35327519, 2022). "Another retrospective analysis included 112 advanced melanoma patients (11 AM and 3 mucosal melanoma patients) who received a combination of BRAF and MEK inhibitors." (PMID 36125617, 2022). "Detection of BRAFV600 mutation (with V600E being the most frequent aberration and V600K being the second one) in melanoma cells qualifies the patient for targeted therapy with BRAF, MEK inhibitors (BRAFi/MEKi)." (PMID 35565444, 2022). "Combination BRAF and MEK inhibition for mutant BRAF-V600E lung cancer and melanoma have been shown to be effective in preclinical studies and is now standard in clinical practice." (PMID 36010600, 2022). "In BRAF-mutant melanoma, treatment with BRAF inhibitors initially inhibits ERK signaling, followed by a rebound activation of ERK signaling as negative feedback pathways are disrupted." (PMID 35510953, 2022). "Here, the authors show that under metabolic stress NRAS-mutant melanoma cells activate a BRAF-dependent glycolysis pathway for survival, leading to improve efficacy of sorafenib when combined with glycolysis inhibitors." (PMID 36402789, 2022). "As such, tyrosine kinase inhibitors (TKIs) targeting BRAF and MEK proteins block the constitutive activation of the MAPK pathway in patients with BRAF-mutated melanoma, therefore reducing maintenance, development or dissemination of the cancer." (PMID 35159045, 2022). "This led to a phase II multicenter trial (BRIM-2) aimed at testing the efficacy and safety of vemurafenib in patients with advanced BRAF V600E-mutant melanoma who had received at least one prior therapy." (PMID 36358912, 2022). "First, our data revealed that the vast majority of the 243 BRAF-mutant melanoma patients receiving front-line BRAF ± MEKi therapy or CPI therapy eventually showed a relapse of the disease within the median follow-up period of 41 months." (PMID 35565212, 2022). "Epigenetic mechanisms induce melanoma resistance to BRAF and MEK inhibitors, often by upregulating survival pathways functionally analogous to MAPK signaling, as illustrated by the following examples." (PMID 36497341, 2022). "Further investigation would be needed to determine the role of these miRNAs, miR-125b, miR-200c and miR-205, in melanoma patients treated with BRAF inhibitor therapy." (PMID 35326682, 2022). "Combined BRAF and MEK inhibition elicits a rapid response in 68% of patients with advanced melanoma harboring BRAFV600E/K mutation followed, however, by tumour relapse after a median of 11 months." (PMID 36726591, 2022). "We benchmarked the efficiency of the model, trained on patient samples from TCGA on RNA-seq profiles of pre-treatment, and matched post-relapse drug-resistant BRAF mutant melanoma patients." (PMID 36167836, 2022). "The combination of Ganetespid and a MEK inhibitor, TAK-733 (also very effective in conjunctival melanoma cell lines in our study), allowed significant growth reduction in an in vivo model of BRAF resistant melanoma cell lines." (PMID 35326726, 2022).
melanoma (continued). "In some cases, the effects of APR-246 have been examined in combination with azacitidine (in MDS and AML), dabrafenib (in V600 BRAF-mutant melanomas), pembrolizumab (an immunotherapeutic which targets PD-1, also known as Keytruda), and venetoclax." (PMID 35269416, 2022). "Ninety-seven cases of melanoma were tested, with BRAF alterations detected in 42 (43%), including V600E, 22 (23%), and V600K, 16 (16%), with NRAS driver alterations detected in 31 (32%)." (PMID 35323313, 2022). "The current landscape of therapies for advanced melanoma consists primarily of BRAF/MEK inhibitors to target BRAF mutant melanoma, and immunotherapies to target all comers in advanced melanoma." (PMID 35624662, 2022). "We observed a significant increase in SOX10+ melanoma cells in the progressed tumors compared to the tumors prior to BRAF/MEK-inhibition from the same patient." (PMID 35058553, 2022). "Given the rapidly evolving combination treatment landscape, future studies using the KRAS G13D/BRAF V600E isogenic model of drug-resistant melanoma described here should focus on combination PD-L1 and BRAF/MEK inhibitor treatment." (PMID 36358868, 2022). "Here, we have analysed AS in SK-MEL-239 melanoma cells and a BRAF inhibitor (vemurafenib)-resistant derivative that expresses an AS, shortened BRAF V600E transcript." (PMID 35883549, 2022). "BRAF inhibitors are commonly used in targeted therapies for melanoma patients harboring BRAFV600E mutant." (PMID 36210843, 2022). "Because ZIC5 knockdown induced melanoma cell death synergistically with the BRAF inhibitor, A375 melanoma cells were treated with the five candidate compounds with or without the BRAF inhibitor (PLX4032) to assess apoptosis." (PMID 36282887, 2022). "Of those, one of the most common mechanisms in melanoma is the alternative splicing (AS) of BRAF, which occurs in 15–30% of patients." (PMID 35883549, 2022). "Despite the promise of dual BRAF/MEK inhibition as a therapy for BRAF-mutant (BRAF-mut) melanoma, heterogeneous responses have been observed in patients, thus predictors of benefit from therapy are needed." (PMID 35440004, 2022). "After the development of BRAF inhibitor resistance, melanoma cell lines exhibit elevated levels of ROS and expression of SOD2." (PMID 35326683, 2022). "Due to the importance of the MAPK pathway in melanoma, the first targeted therapies were small-molecule inhibitors of BRAF (vemurafenib, dabrafenib), which were followed by combination therapies with BRAF and MEK inhibitors." (PMID 35804857, 2022). "Preclinical studies using mouse melanoma models and patient samples have revealed that BRAF/MEKi initially induce an immune-stimulatory TME, which contributes to their therapeutic activity." (PMID 35366166, 2022). "Supporting the efficacy of the BRAF inhibitor against BRAF(V600E)-mutant melanoma, a recent study suggested that BRAF inhibition directly enhanced NK cells’ immunostimulatory capacity via upregulating CD69 expression and IFNR release." (PMID 36145516, 2022). "Antiapoptotic inhibitors of the BCL-2 family synergize with tetrathiomolybdate to induce apoptosis in melanoma cells resistant to BRAF and MEK1/2 inhibitors." (PMID 36581992, 2022). "In that same study, the knockdown of SOD2 expression in resistant melanoma cells inhibited proliferation, while the administration of the exogenous antioxidant, N-acetyl cysteine, re-sensitized resistant cells to BRAF-inhibitor treatment." (PMID 35326683, 2022). "Mechanistically, the authors found that in both BRAF and NRAS mutated melanomas, MEK inhibition increases MITF expression, which, in turn, upregulates the expression of PGC-1α." (PMID 36077374, 2022).
melanoma (continued). "The fact that both melanoma and PTC are frequently characterized by activating mutations of the BRAF gene suggests the presence of shared etiologic events." (PMID 36077430, 2022). "Previous studies based on mice demonstrated that BRAF inhibitor response durations in vivo were significantly longer when melanoma cell lines were grown in immunocompetent mice compared to immunocompromised." (PMID 36531226, 2022). "Here, we utilized melanoma cell lines with BRAF mutant to study, in the hope of developing new target inhibitors to reduce the occurrence of drug resistance." (PMID 36387162, 2022). "More specifically, in MITFlowAXLhigh melanoma cells that were resistant to the BRAF inhibitor Vemurafenib, increased actin stress-fiber formation and remodeling were observed, which were shown to be dependent on increased levels of nuclear YAP/TAZ." (PMID 36119516, 2022). "Treatment with inhibitors of the BRAF/MEK pathways provides significant benefit in patients with BRAF-mutant advanced melanoma." (PMID 35954369, 2022). "They found that tumor growth and metastasis were reduced in inducible and experimental BRAF-mutant melanoma treated with the combination therapy targeting BRAF and A2AR." (PMID 36131912, 2022). "In our series, patients with BRAF and MET genetic alterations did not receive any targeted treatment because no such treatment were available at the time of the study, despite BRAF was a well-established therapeutic target in other malignancies like melanoma." (PMID 35012520, 2022). "All these patients with advanced melanoma were treated with MAPKi (either BRAFI monotherapy or combo therapy with a BRAF and a MEK inhibitor) as first line therapy." (PMID 36438490, 2022). "For this purpose, the BRAF-mut melanoma cell line 2/59 was engineered for inducible silencing of SEMA6A expression and induction of GFP reporter gene expression." (PMID 35440004, 2022). "In this study, we have demonstrated how CRISPR/Cas9 genome engineering can be used to create novel, physiologically relevant cell-based models of acquired BRAF inhibitor resistance in BRAF V600E melanoma." (PMID 36358868, 2022). "Very recent work suggests that post-transcriptional regulation of metabolic genes following BRAF inhibition plays a central role in the adaptation of BRAFV600E melanoma cells via translational reprogramming." (PMID 36077374, 2022). "In 2011 the FDA approved the use of vemurafenib, a BRAF inhibitor, for patients with advanced melanoma, as a result of which rates of OS and PFS improved significantly." (PMID 35628540, 2022). "Type I IFN signaling is involved in the regulation of oncogene-induced senescence, therefore it was studied in BRAF-mutant melanocytes and melanomas in animal models." (PMID 35269844, 2022). "The importance of trial duration on success is demonstrated by the MK-3475-022/KEYNOTE-022 trial of pembrolizumab with dabrafenib and trametinib for BRAF-mutant melanoma." (PMID 35169116, 2022). "Several melanoma therapies targeting constitutively activated BRAF have been investigated in recent years, with several approaching therapeutic approval." (PMID 35954441, 2022). "For example, intra-vital imaging of BRAF-mutant melanoma cells containing an ERK/MAPK biosensor revealed how the extracellular matrix affected the response to the BRAF inhibitor PLX4720." (PMID 36324182, 2022). "Similar to the previous results, BV (96.3 ± 1.1%) and LV (93.9 ± 1.2%) in the vem + pic group were notably more viable than those in other groups, owing to the effective suppression of melanoma invasion and proliferation by BRAF/PI3K combined inhibition." (PMID 36026581, 2022). "BRAF is found in only around 5% of spitz neoplasms, most of which appears to fall into the Spitz Melanoma category at least in one series." (PMID 35747831, 2022). "Some specific driver mutations have been described in multiple oncogenes including BRAF and NRAS that are mutated in 60–70% and 15–20% of melanoma, respectively." (PMID 36400750, 2022).